MMP9 (matrix metallopeptidase 9)
Diseases named in the same sentence as MMP9 in open-access papers (continued):
Sharing a sentence is not in itself a finding about the gene and the disease.
tumor (continued). "Consistent with the epigenetic regulation of miRNAs we further showed that demethylation agent or HDAC inhibitor inhibited the secretion of MMP-2 and MMP-9 in EC cells, which further proves that epigenetic regulation of miRNAs play a role in the regulation of EMT and tumor metastasis of EC." (PMID 23680357, 2013). "Moreover, miR-21 can downregulate tissue inhibitor of MMPs-3 (TIMP3) and reversion-inducing cysteine-rich protein with Kazal motifs (RECK), which are both MMP-9 inhibitors, resulting in elevated MMP-9 activation and enhanced tumor cell invasion." (PMID 24202447, 2013). "It further supports that IL-19 not only directly facilitates cell proliferation, cell migration, and metastasis but it also prompts the expression of IL-1β, IL-6, TGF-β, MMP-2, MMP9, CXCR4, and fibronectin, which supply of a microenvironment for tumor growth and metastasis." (PMID 23710200, 2013). "Additionally, CD44, which is known to promote tumor cell motility and invasion, can anchor active MMP-9 to the cell surface, and has been localized with MMP-9 and MT1-MMP on cellular invadipodia." (PMID 24194929, 2013). "This may have been due to the decrease in the protein expression of MMP-9, PCNA and VEGF, and the increase in the TIMP-1 protein expression induced by SN50, in combination with the cytotoxicity of SN50 towards the tumor cells." (PMID 24137341, 2013). "With respect to expression of both MMP-9 and TIMP-2, MG63 exhibited the most pronounced upregulation response to an in vitro microenvironment that most resembled in vivo tumor growth conditions; both of these biomarkers are consistently expressed in OS biopsy samples." (PMID 23914349, 2013). "Matrix metalloproteinase-9 (MMP-9), tissue inhibitor of metalloproteinases type-1 (TIMP-1) and vascular endothelial growth factor (VEGF) are important angiogenic factors that have a higher expression level in tumor tissues." (PMID 24137341, 2013). "Consistently, TGF-β1/H2O2/HOCl was most efficient in promoting the polymerization of actin in tumor cells and the production of active MMP-2 and MMP-9 by tumor cells in response to ECM molecules (matrigel), which are important for migratory and invasive properties of tumor cells." (PMID 24260309, 2013). "Among MMPs, MMP-2 and MMP-9 play a critical role in the modification of ECM and tumour invasion." (PMID 23641796, 2013). "MMP-9 is capable of degrading collagen IV, a main component of the ECM and basement membrane, and thus plays an important role in the invasion and metastasis of tumor cells." (PMID 24312291, 2013). "It should also be mentioned that stable concentrations of MMPs, with possible fall of free MMP-9, do not support a notions of significant involvement of MMPs in the development of neoplasms following treatment with radioactive iodine." (PMID 23919647, 2013). "To test whether increased expression of TIMP-1 induces expression of the EMT markers, we analyzed the tumor sections derived from the in vivo experiments for the expression of Snail, Slug, MMP-2, and MMP-9." (PMID 24143225, 2013). "Blocking MMP-2 and MMP-9 with MMP inhibitors or antibodies against MMP-2 or/and MMP-9 partially rescues the invasion and metastasis effects thus providing direct evidence for the role of astrocyte-secreted MMP-2 and MMP-9 in tumor invasion and brain metastasis." (PMID 24324647, 2013). "From the Cox proportional hazards analysis neither the PLA measurements of MMP-9:TIMP-1 (Q2, Q3, or Q4) nor menopausal status, tumor size, lymph node status, or malignancy grade were associated with DFS." (PMID 24330623, 2013). "In tumor angiogenesis studies using MMP-9 knockout mice, transplanting tumors are unable to grow after irradiation in MMP-9 knockout mice, but tumor growth could be restored by transplantation of wild-type bone marrow." (PMID 23840100, 2013). "MMP-2, MMP-9 and MT1-MMP mRNA expression increased significantly with the TNM stage of the tumor." (PMID 23281640, 2013).
tumor (continued). "Furthermore, the necrotic areas that extended from the cores to breach the tumor surface in scorbutic mice were surrounded with TUNEL apoptosis staining and directly coincided with MMP-9 staining areas." (PMID 23175106, 2013). "Analysis of RABEX-5 and MMP-9 expression in tumors derived from the MCF-7/NC group indicated strong staining throughout the tumor mass, whereas tumors from the MCF-7/KD group showed less staining only in part of the areas of the tumor mass." (PMID 23941575, 2013). "Moreover, in the tumor sections, the presence of the GLUT-1 and EGFR, as well as the expression of MMP-9 and Cathepsin B, was shown by immunohistochemistry as well as indicated by FLI." (PMID 22348134, 2012). "It is noted that relatively high levels of MMP9 and MMP3 in the patient tumor sample were detected." (PMID 22873525, 2012). "Because FoxM1 silencing inhibited the expression and activity of MMP-2, MMP-9 and VEGF that are thought to be critically involved in the processes of tumor cell migration, invasion and metastasis, we tested the effect of FoxM1 deletion on cancer cell migration and invasion." (PMID 23006512, 2012). "Since tissue samples are composed of cancer cells and surrounding non-cancer cells,which is the components of tumor microenvironment, we think that MMP-9 is secreted mainly by the non-cancer cell in tumor microenvironment." (PMID 22546345, 2012). "They observed a significant decrease in tumor growth accompanied by downmodulation of the nuclear factor-kappaB (NF-κB) expression and transcriptional activity, and consequently in significant inhibition of MMP-2 and MMP-9 expression." (PMID 22811704, 2012). "Reduced expression of ICAM-1, MMP-9 and VEGF might be responsible for diminished invasion of tumor cells in cryptopleurine treatment." (PMID 22768286, 2012). "In this study, we found that co-culturing the SACC-LM cells and fibroblasts to mimic the tumor-stroma interactions produced elevated levels of MMP-2 and MMP-9 and gave rise to greatly increased in vitro invasion activity of SACC-LM cells, as compared with cultures of SACC-LM cells alone." (PMID 22200897, 2012). "Furthermore, NGAL assists tumor growth and angiogenesis by forming complexes with MMP-9, thereby protecting MMP-9 from degradation." (PMID 23056218, 2012). "It has been demonstrated that transgenic mice lacking MMP-9 show reduced keratinocyte hyper proliferation at all neoplastic stages and a decreased incidence of invasive tumours." (PMID 23905066, 2012). "Serum derived from transgenic (but not non-transgenic) mice led to enhanced transcription as well as expression of VEGF, IL-8, KC (murine IL-8) and MMP-9 in tumor cells, effects not seen when sera derived from hCG-immunized transgenic mice was employed." (PMID 23226476, 2012). "In Dukes’ B and C of the validation series, we noticed poorer prognosis among patients with MMP-9 negative tumours, but the differences were not significant." (PMID 23216739, 2012). "Crosslinking of collagen by LOXL2 may stimulate matrix metalloproteinases such as MMP9 and TIMP1 to implement ECM remodeling (interaction 20), thereby facilitating tumor cell migration." (PMID 22570691, 2012). "Additional NF-κB target genes which contribute tumor cell migration and/or metastasis include cellular adhesion molecular, such as ICAM-1 and VCAM-1; matrix metalloproteinases, such as MMP-9; chemokine receptors, such as CXCR4, and vascular endothelial growth factor (VEGF)." (PMID 22952718, 2012). "Regarding tumor recurrence, we observed that patients with tumor recurrence showed higher expression of MMP-9 and IL-8 when compared with patients that not recurred (p = 0.003; p = 0.005)." (PMID 22695075, 2012). "MMP-9 immunopositivity did not correlate with Dukes’ stage, but was more often positive in local (Dukes’ A-B) tumours than in advanced disease (p = 0.016 )." (PMID 23216739, 2012).
tumor (continued). "Furthermore, the dose-dependent TGF-β1 functions on MMP-9 and RECK protein levels emphasize the multifaceted mechanism of this cytokine in the control of tumor invasion and metastatic capacities." (PMID 22260435, 2012). "STAT3 relevance in oncogenesis/tumor progression is widely acknowledged, via regulating apoptosis-related genes (Bcl-XL, Mcl-1 and Survivin), proliferation- (c-myc and cyclin D1) and invasion-promoting genes (VEGF, MMP-9)." (PMID 23028842, 2012). "MMP-9 and TIMP-1 have significant potential tumor marker impact in CRC." (PMID 23202950, 2012). "Importantly, EBP1 downregulates MMP9 but enhances the protein levels of E-cadherin and another critical molecule, ICAM-1, which is involved in tumor immunity and metastasis." (PMID 23110497, 2012). "This increased tumor growth and metastasis formation could be attributed to the IL-8-mediated up-regulation of the metalloproteinases MMP-2 and MMP-9 expression and activity." (PMID 22811704, 2012). "We presumed that the downregulation of MMP-2, MMP-9 and MMP-14 might alleviate the extracellular matrix (ECM) degradation, thus maintaining the vascular basement membrane and normalizing tumor vasculature." (PMID 22496834, 2012). "The tissue levels of MMP-9, either from normal mucosa or tumour, did not correlate and were also independent from the genotypic background." (PMID 22472880, 2012). "Regardless of the tumor type, the band for pro-MMP-9 was significantly more evident in the plasma of dogs with tumors than in healthy dogs." (PMID 21726449, 2011). "We demonstrated that tumours cannot grow in an irradiated site (given 20 Gy) of an MMP-9 knockout (KO) mouse but can grow in a non-irradiated MMP-9 KO mouse." (PMID 21587260, 2011). "The initial step of tumor cell invasion is characterized by the breakdown of the base membrane, a process known to be dependent on type IV collagen-degrading enzymes, mainly MMP-2 and MMP-9." (PMID 21955589, 2011). "Finally, known tumor-promoting downstream effectors of JNK1 and STAT3 displayed enhanced expression (e.g., Myc, Jun, Mmp9, and Vegfa), which was restricted to DKO livers." (PMID 21725989, 2011). "In addition, MMP-1 and MMP-9 were found to be regulated by STAT3, which plays a crucial role in tumor invasion and metastasis." (PMID 21991388, 2011). "It seemed likely that the function of LIV-1 was to stimulate the expression of MMP2, MMP9 and HB-EGF proteins, which in turn activated EGFR and downstream ERK signaling, leading to EMT that facilitated local tumor growth and its distant metastases to bone and soft tissues." (PMID 22110740, 2011). "We recently reported that CD248CyD/CyD fibroblasts express reduced amounts of VEGF, PlGF and active MMP-9 and considered that other soluble factors might be secreted in a CD248-dependent manner that regulate tumor cell proliferation." (PMID 21549007, 2011). "With such a profound effect on the expression of β1-integrin (as previously shown) and MMP-9 it is not surprising that tumor cell metaststatic actvity is reduced in a hypertonic environment." (PMID 29147264, 2011). "MMP-2, MMP-9 and MT1-MMP were expressed at both the mRNA and protein levels in tumor samples." (PMID 21726449, 2011). "Unlike CD11b+ monocytes/macrophages in non-irradiated tumours, these cells express the angiopoietin-2 receptor Tie-2 as well as MMP-9 and the F4/80 macrophage marker, and are therefore classified as Tie-2-expressing macrophages (TEMs)." (PMID 21587260, 2011). "For example, the production of pro-angiogenic factors, including VEGF, and of tumor invasion related enzymes, such as MMP2 and MMP9, was upregulated in vitro by norepinephrine in several human and non-human cancers, through the β-adrenergic-cAMP-PKA pathway in tumor cells." (PMID 21559428, 2011). "Another interesting example is the effects of macrophages on tumor development, which mainly depends on whether they secrete anti-tumor factors IL-12 and TNF-α, or pro-tumor factors IL-10, VEGF, PDGF, CXCL8, MMP-9 and TGF-β." (PMID 21760911, 2011).
tumor (continued). "Our results may indicate that MMP9 plays significant roles in NPC progression, including tumor invasion and metastasis." (PMID 20534121, 2010). "Furthermore, MA decreased the expression levels of NF-κB-regulated genes, including genes involved in tumor cell proliferation (Cyclin D1, COX-2 and c-Myc), apoptosis (Survivin, Bcl-2, Bcl-xl, XIAP, IAP-1), invasion (MMP-9 and ICAM-1), and angiogenesis (VEGF)." (PMID 20367887, 2010). "Study using breast cancer samples demonstrates that the expressions of MMP-1, MMP-2, MMP-3, MMP-9, urokinase-type PA, and tissue-type PA, and inhibitors (TIMP-1 and TIMP-2) were stronger or equivalent in tumor cells than in fibroblasts or inflammatory cells within the tumor section." (PMID 21152266, 2010). "Secondly, residual hepatic VX2 carcinoma might facilitate rapid tumor progression through induction of overexpression of multiple molecular factors, such as PCNA, MMP-9, VEGF, HGF and IL-6." (PMID 20667141, 2010). "Moreover, it has been shown that Her2 overexpression is related with the invasion capacity of the tumor cells that is related partly with the up-regulation of MMP-2 and MMP-9 expression as well as proteolytic activity." (PMID 20482751, 2010). "MMP9 mRNA was not expressed by the tumour and this was confirmed by negative staining with MMP9 antibody on cryosections and lack of activity in zymograms (data not shown)." (PMID 19292920, 2009). "Expressed in embryonic development, matrix metalloprotein-9 (MMP-9) is absent in most of developed adult tissues, but recurs in inflammation during tissue injury, wound healing, tumor formation and metastasis." (PMID 19298660, 2009). "Activation of MMP9 could liberate EGFR ligands from the extracellular matrix, thereby promoting HNSCC tumor progression through increased EGFR signalling." (PMID 20066159, 2009). "As for the demonstrated increase in MMP-9, it is worth noting that it was shown earlier to be elevated in saliva and that strong stromal MMP-9-staining intensity was correlated with poor tumour differentiation." (PMID 19789535, 2009). "In a random series of 110 HCC patients, the mRNA of HIF-1alpha, inflammation related factors (COX-2, MMP7 and MMP9), angiogenesis related factors (VEGF and PDGFRA) and MYC in tumor tissue were detected by real-time RT-PCR and HIF-1alpha protein was assessed by immunohistochemistry." (PMID 19948069, 2009). "Tumor cell adhesion and migration, as well as metalloproteinase MMP-9 activity, decreased in the presence of 1 μM RGZ (non-cytotoxic dose)." (PMID 18261208, 2008). "Tumor tissues derived from curcumin treated mice showed that curcumin inhibibited proliferation (PCNA and Ki67 staining), induced apoptosis (TUNEL staining), metastasis (uPA, MMP-2 and MMP-9 staining), and angiogenesis (CD31 and VEGF staining)." (PMID 18226269, 2008). "Almost all tumor cells were positive for MMP-2 and MMP-9 staining." (PMID 18983683, 2008). "The results of real time PCR show that thalidomide could down-regulate MMP-2 and MMP-9 mRNA expression, suggesting that thalidomide can inhibit tumor growth via down-regulation of the MMP-2 and MMP-9 mRNA level." (PMID 18983651, 2008). "The Omnibus test showed non-significant differences between clinical stage at diagnosis, Clark level, tumor thickness, tumor site, and phenotypic index, and the MMP-9 haplotypes (data not shown)." (PMID 17346338, 2007). "Unlike the fibroblast invasion assay alone, FaDu tumor cells in coculture with MMP-2 null fibroblasts demonstrated 50% less invasion compared to FaDu cells in coculture with MMP-9 null or WT fibroblasts." (PMID 16515711, 2006). "Analysis of conditioned media obtained from cells cocultured on type I collagen demonstrates that fibroblasts and not tumor cells express proMMP-2 and MMP-9." (PMID 16515711, 2006).
tumor (continued). "Incubation of sub-confluent FaDu tumor cells atop type I collagen with serum-free conditioned media from WT, MMP-2 null, MMP-9 null or MT1-MMP null fibroblasts failed to induce FaDU tumor cell invasion (data not shown) over a 7 day incubation period." (PMID 16515711, 2006). "Particularly remarkable is the presence of more active MMP-2, but not of active MMP-9, in the tumour tissue homogenates." (PMID 16538217, 2006). "By using immunohistochemical staining, we found that no expression of PCNA, CD44v6, and MMP-9 of the treated tumour cells was identified in the HIFU group, unlike those in the control group." (PMID 14676799, 2003). "However, it would be unjustified to conclude from this that the role of MMP-9 in tumour invasion and progression would be less important than that of MMP-2, which shows increased activation in tumour." (PMID 12085179, 2002). "It is suggested that MMP-9 levels reflect the presence of inflammatory infiltrate around the tumour rather than the characteristics of the tumour itself." (PMID 12085179, 2002). "The matrix metalloproteinases MMP-2 (72 kDa gelatinase) and MMP-9 (92 kDa gelatinase), which play a key role in invasion in other tumours, are not affected by RA." (PMID 10507760, 1999). "Positive expression of MMP-2 in tumour epithelium and of MMP-9 in tumour-infiltrating macrophages were both independent of tumour stage and were without correlation with survival time." (PMID 9310250, 1997). "A large number of MMP-9-positive macrophages correlated (P < 0.05) with poor tumour differentiation, whereas weak or absent epithelial MMP-2 staining reached near significance (P < 0.08)." (PMID 9310250, 1997). "In liver metastases, MMP-9 localised within peritumour stroma or at the interface between the tumour stroma and normal liver, whereas TIMP-1 mRNA was located throughout the malignant tumour stroma." (PMID 7669564, 1995). "In this context, SLPI overexpression was associated with increased MMP-9 activity, upregulation of VEGFA and VE-cadherin, and suppression of N-cadherin—molecular features that are characteristic of VM-competent tumor cells rather than endothelial-dependent angiogenesis." (PMID 41557653, 2026). "Furthermore, intratumoral bacteria can indirectly stimulate neutrophils to overexpress NE and matrix metalloproteinase-9 (MMP-9), resulting in polymorphonuclear leukocyte (PMN) activation and NET formation as a physical barrier between tumor cells and NK cells, mediating innate immune escape." (PMID 41326352, 2025). "In addition to MMP9, we identified several factors regulated by ADAMTS13 that play a decisive role in the formation of blood vessels and can therefore significantly influence tumor growth." (PMID 41211185, 2025). "Thus, this study aimed to clarify the role of RAD23B in CRC metastasis and to explore the molecular mechanisms by which it regulates tumor cell migration, invasion, and metastasis through the Talin1/Integrin β1/PI3K/AKT/matrix metalloproteinase 9 (MMP9) signaling axis." (PMID 41179295, 2025). "Moreover, Mmp9 promotes VEGF activation and tumor angiogenesis." (PMID 39425000, 2025). "Indeed, DNJ has been shown to inhibit the expression of MMP2 and MMP9, upregulate TIMP-2, and alter cell surface glycan-binding motifs, which are crucial in extracellular matrix remodeling, differentiation, and migration of tumor-derived cells." (PMID 40428492, 2025). "For example, they can release molecules that promote tumor angiogenesis, such as vascular endothelial growth factor-A (VEGF-A), transforming growth factor-β (TGF-β), heparin, interleukin-8 (IL-8), matrix metalloproteinase-9 (MMP-9), trypsin-like proteases, and chymotrypsin." (PMID 40703522, 2025). "In addition, APS inhibited the overactivation of p-AKT and the overexpression of Matrix metalloproteinase-9 (MMP-9), attenuating the promotion of tumor cell proliferation and migration, indicating that APS-induced autophagy and apoptosis assist each other in the anti-GC effect." (PMID 40066330, 2025).